ANO3 (anoctamin 3)
Description:
Has calcium-dependent phospholipid scramblase activity; scrambles phosphatidylcholine and galactosylceramide (By similarity). Seems to act as potassium channel regulator and may inhibit pain signaling; can facilitate KCNT1/Slack channel activity by promoting its full single-channel conductance at very low sodium concentrations and by increasing its sodium sensitivity (By similarity). Does not exhibit calcium-activated chloride channel (CaCC) activity.
Synonyms: C11orf25; TMEM16C; GENX-3947; DYT23; DYT24
Tractability: Antibody: UniProt places it where antibodies can reach, with high confidence; its Gene Ontology location is reachable by antibodies, with high confidence; UniProt predicts a signal peptide or a membrane-spanning region.
Gene: Protein-coding gene on chromosome 11 (26,188,842 to 26,663,289, forward strand). Ensembl gene ENSG00000134343.
Subcellular location: Cell membrane
Subcellular location (Human Protein Atlas): Cytosol; Microtubules; Primary cilium; Basal body; Mitotic spindle
Pathways (Reactome):
Disease: Induction of Cell-Cell Fusion
Transport of small molecules: Stimuli-sensing channels
Gene Ontology:
Molecular function: intracellularly calcium-gated chloride channel activity; chloride channel activity; phospholipid scramblase activity; protein dimerization activity
Biological process: monoatomic ion transmembrane transport; phospholipid translocation; chloride transmembrane transport; detection of mechanical stimulus; detection of temperature stimulus; plasma membrane phospholipid scrambling
Cellular component: cilium; plasma membrane
Genetic constraint (gnomAD): Loss-of-function variants: 70 observed, 93.71 expected, observed/expected ratio (o/e) 0.75, 90% interval 0.62 to 0.91. The upper end of that interval is the gene's LOEUF score, 0.91, which puts it in group 3 of 6, group 1 being the genes least tolerant of losing a copy. Missense variants: 674 observed, 910.07 expected, observed/expected ratio (o/e) 0.74, 90% interval 0.69 to 0.79. Synonymous variants: 299 observed, 305.54 expected, observed/expected ratio (o/e) 0.98, 90% interval 0.89 to 1.08.
Homologues: Orthologues: macaque ANO3 (99% identical), chimpanzee ANO3 (99% identical), guinea pig ANO3 (95% identical), rabbit ANO3 (94% identical), pig ANO3 (94% identical), rat Ano3 (94% identical), mouse Ano3 (94% identical), dog ANO3 (93% identical), tropical clawed frog ano3 (72% identical), zebrafish ano3 (71% identical). Paralogues in human: ANO4 (60% identical), ANO5 (38% identical), ANO6 (38% identical), ANO2 (38% identical), ANO1 (37% identical), ANO7 (33% identical), ANO9 (29% identical), ANO8 (21% identical), ANO10 (18% identical), PPP1R7 (9% identical).